GJA10 (gap junction protein alpha 10)
Description:
One gap junction consists of a cluster of closely packed pairs of transmembrane channels, the connexons, through which materials of low MW diffuse from one cell to a neighboring cell. Involved in tracer coupling between horizontal cells of the retina. May play a role in the regulation of horizontal cell patterning (By similarity).
Synonyms: Cx62
Tractability: Antibody: its Gene Ontology location is reachable by antibodies, with high confidence; UniProt places it where antibodies can reach, with medium confidence; UniProt predicts a signal peptide or a membrane-spanning region.
Gene: Protein-coding gene on chromosome 6 (89,894,469 to 89,921,760, forward strand). Ensembl gene ENSG00000135355.
Subcellular location: Cell membrane; Cell junction, gap junction
Pathways (Reactome):
Neuronal System: Electric Transmission Across Gap Junctions
Vesicle-mediated transport: Gap junction assembly
Gene Ontology:
Molecular function: gap junction channel activity
Biological process: cell-cell signaling; cell communication; transmembrane transport
Cellular component: connexin complex; plasma membrane; gap junction
Genetic constraint (gnomAD): Loss-of-function variants: 2 observed, 0.63 expected, observed/expected ratio (o/e) 3.17. That is too few expected variants to judge how well the gene tolerates losing a copy. Missense variants: 685 observed, 689.51 expected, observed/expected ratio (o/e) 0.99, 90% interval 0.93 to 1.06. Synonymous variants: 239 observed, 247.18 expected, observed/expected ratio (o/e) 0.97, 90% interval 0.87 to 1.08.
Homologues: Orthologues: macaque GJA10 (97% identical), chimpanzee GJA10 (88% identical), pig GJA10 (75% identical), rabbit GJA10 (74% identical), mouse Gja10 (73% identical), dog GJA10 (73% identical), rat Gja10 (72% identical), guinea pig GJA10 (66% identical), tropical clawed frog gja10 (43% identical), zebrafish gja10b (41% identical), zebrafish gja10a (40% identical). Paralogues in human: GJA9 (37% identical), GJA8 (27% identical), GJA3 (26% identical), GJA5 (26% identical), GJA4 (25% identical), GJA1 (24% identical), GJC1 (21% identical), GJC2 (20% identical), GJB2 (19% identical), GJD2 (19% identical), GJB1 (19% identical), GJB4 (18% identical), and 8 more.
Diseases named in the same sentence as GJA10 in open-access papers:
GJA10 is named in the same sentence as 5 diseases in open-access papers, as found by Europe PMC text mining. Sharing a sentence is not in itself a finding about the gene and the disease. The quoted sentences say what the papers report.
leukemia (1 paper, 2018). A malignant (clonal) hematologic disorder, involving hematopoietic stem cells and characterized by the presence of primitive or atypical myeloid or lymphoid cells in the bone marrow and the blood. "We assume that all three genes located between MAP3K7 and CASP8AP2 (GJA10, BACH2, MIR4464) and a variable number of adjacent genes are co-deleted in these leukemias." (PMID 29914415, 2018).
GJA10 also shares sentences with these, for which no sentence is quoted: tumor (2 papers); cancer (1); deafness (1); prostate carcinoma (1).